CD68 (CD68 molecule)
Diseases named in the same sentence as CD68 in open-access papers (continued):
Sharing a sentence is not in itself a finding about the gene and the disease.
tumor (continued). "Immunohistochemical analysis of CD68+ macrophages was performed on 58 human and 59 canine tumor samples." (PMID 40725175, 2025). "CD68+ macrophages infiltrated most samples and they were significantly more abundant in the tumor necropsies, compared to control brainstem samples." (PMID 40703808, 2025). "The elevated CT/IM ratios for CD8+ T cells, CD20+ B cells, and CD68+ macrophages in OCRC indicate a shift toward immune cell enrichment in the tumor core, contrary to the typical "immune-excluded" phenotype seen in advanced CRC." (PMID 41301691, 2025). "The rest of the tumor immune microenvironment was represented by CD68 positive macrophages (20%) and plasma cells (10%)." (PMID 40075893, 2025). "Among the most established biomarkers are members of the scavenger receptor family, such as CD206, CD163, stabilin-1, Marco, CD36, and CD204, which are expressed on CD68+ macrophages in tumor tissues." (PMID 41417432, 2025). "A similar association with a gradual increase of infiltration by TILs, TAMs, CD8, CD68 as well as the CD68/CD163 ratio was observed for tumour size (pTis →pT1→pT2)." (PMID 41018083, 2025). "A positive correlation was detected between the number of tumor-infiltering CD68 + macrophages and the CCL2 intensity score (p = 0.008, r = 0.695)." (PMID 40064752, 2025). "In summary, NSG-Quad mice supported the development of different human myeloid cell lineages and promoted the development of tissue-resident as well as tumor-infiltrating human CD68+ macrophages at a level almost comparable to MISTRG-6 mice." (PMID 40503011, 2025). "Our data partially agree with these findings, as the abundance of macrophages (CD68 +) was associated with ccRCC aggressiveness and worse CSS, with similar associations observed at the tumor center and periphery." (PMID 39751643, 2025). "Immunohistochemical staining of the second resection specimen showed that tumor cells were positive for CD68, CD163, CD4, INI-1 and ATRX, Scattered focal positivity for lysozyme, and some positive for S-100 and LCA." (PMID 40231251, 2025). "Immunohistochemical profile of tumor cells in our patient showed vimentin, CD68, and alpha-SMA positivity." (PMID 40283372, 2025). "CD68+ infiltrating macrophages were predominantly in the tumor core, and TMEM119+ resident macrophages (microglia) were clustered in invasive islands." (PMID 39781357, 2025). "In ccRCC specimens exhibiting CCL5 upregulation, a significant increase was observed in both CCL5+ tumor-associated macrophages (TAMs) and PD-L1+ CD68+ TAM populations, indicative of an immunosuppressive tumor immune microenvironment (TIME)." (PMID 40396123, 2025). "The majority of CD68+ TAMs were located in peripheral regions of the tumor mass, where they formed dense peristromal clusters." (PMID 40843751, 2025). "In our study, significantly increased CD68 expression was observed in ART-treated animals at weeks 12 and 16, possibly indicating the recruitment of tumor-associated macrophages, particularly of the M2 phenotype, known for their pro-tumoral role." (PMID 40943044, 2025). "The protein levels of macrophage-related genes, including CD163, CD14, and CD68, were assessed using immunohistochemistry (IHC) on tumor tissues and adjacent tissue microarray." (PMID 40270962, 2025). "The prominent increase in CD68+ and CD163+macrophages suggests their important role in tumor-associated immunomodulation." (PMID 41007741, 2025). "In glioma macrophages, CCL3 is a marker of the anti-tumor fraction, while CD68 and CD163 are markers of the pro-tumor fraction." (PMID 40191211, 2025). "CD70 was also expressed by the majority of CD68 + TAMs in both the stroma and tumor compartments, while CD3 + T-cells showed limited CD70 expression." (PMID 40205178, 2025). "Immunohistochemistry showed that the tumor cells were positive for molecules such as CD68 and CD163." (PMID 40231251, 2025).
tumor (continued). "In FGFR2+ TMEs, we confirmed that the node in the network associated with tumor cells was generally distant from the CD8+ T-cell effector immune cell types and near CD11b+/CD15+ granulocytes and CD68+/CD163+ macrophages." (PMID 39969434, 2025). "Compared with the Chemo group, there was a higher density of CD68+ cells in tumor in the Io+Chemo group (p=0.000)." (PMID 39931056, 2025). "Immunohistochemistry showed strong positivity for CD163 and CD68, indicating a histiocytic lineage in the tumor cells." (PMID 40901224, 2025). "Based on the IMC findings, CD163 was included to identify most macrophages and the dual staining with CD68 supported the distinction between macrophages and tumor cells." (PMID 40601026, 2025). "Tumor samples were examined histologically and immunohistochemically for CD68+ and CD163+ macrophages, and quantitative analysis was performed in intratumoral and peritumoral regions." (PMID 41007741, 2025). "TC demonstrated an immune-rich profile representing abundant tumor-associated CD8+ lymphocytes, CD68 and CD163+ macrophages." (PMID 39936166, 2025). "Our investigation into the tumor microenvironment highlights the complex roles of macrophages (CD68+) and T-cells (CD4+, CD8+)." (PMID 40599139, 2025). "In the tumor parenchyma, the infiltrating immune cells were primarily CD68+ macrophages; while in the stroma, CD4+ T cells were dominant." (PMID 40710213, 2025). "In the 3D model, M2-polarised macrophages (CD68 + CD163 + TMEM119 -) that had been validated by ICC were co-cultured with tumour cells." (PMID 40420192, 2025). "Immunohistochemical analysis using anti-CD68 antibodies revealed pronounced heterogeneity in macrophage infiltration—both between cases and within individual tumor samples." (PMID 40843751, 2025). "CD68 staining was detected in 244 of 246 tumor tissues (99%) and 241 of 246 tumor‐ adjacent mucosa samples (98%)." (PMID 36811271, 2024). "Tumor-associated macrophages (TAMs) demonstrated significant upregulation of CD163, CD68, and CSF1R." (PMID 39484208, 2024). "Aneuploidy, notably uniparental disomy (UPD), homologous recombination deficiency (HRD), epithelial-mesenchymal transition and inflammation with CD68+ monocytes were identified as tumour-intrinsic resistance factors." (PMID 39168966, 2024). "In our study, VISTA expression was identified in inflammatory cells (lymphocytes and macrophages) in the tumor microenvironment and was identified by their morphological appearance in HE stains and by immunolabeling with CD68 and CD3." (PMID 38673920, 2024). "The quantity of macrophages varies depending on the tumor stage, with a notably greater amount of CD68+ macrophages in the tumor-stage compared to early-stage folliculotropic MF." (PMID 39703508, 2024). "The proportions of CD68+ SHP2+ cells (P < 0.05) and CD68+CD206+ SHP2+ cells (P < 0.0001) were higher in tumor than in stroma." (PMID 38799432, 2024). "A major finding was a decrease in CD68-expressing macrophages, which was observed in the whole tumor tissue as well as in the stromal compartment." (PMID 38474362, 2024). "Mucosal and submucosal infiltration of CD68-positive cells increased in the non-tumor areas in the AOM/DSS model." (PMID 38540144, 2024). "TAMs are often identified by CD11b and CD68, with markers such as IFN-γ and HLA-DR associated with an anti-tumor phenotype, while CD163, CD206, PD-L1 and ARG1 are associated with a tumor-promoting phenotype." (PMID 39310770, 2024). "We conducted double immunofluorescence staining of Ki67 and CD68 in HCC tumor tissues from our previous cohort, and compared the level of Ki67+CD68+ cells between male and female patients." (PMID 39582864, 2024). "VISTA has been identified as a powerful inhibitory checkpoint on CD68+ macrophages when comparing a tumor that responds well to immunotherapy with a tumor that does not respond well to immunotherapy." (PMID 38357542, 2024).
tumor (continued). "In the example shown here, we visualized expression of Ecad, CD8a, and CD68, which are markers for epithelial and tumor cells, CD8+ T cells, and macrophages, respectively." (PMID 38172724, 2024). "Immunohistochemical characterization identified these cells as CD8+, CD4+, CD20+, FOXP3+, CD163+, or CD68+ cells, and the density of each cell type in the tumor-immune microenvironment (TIME) was quantified." (PMID 39272861, 2024). "Consistent with this, using a targeted OIS-PRM approach to quantify immune infiltration, we detected a marked reduction in tumor associated macrophage markers CD163A and CD68 in CPN samples relative to those from CP mice." (PMID 38335300, 2024). "We further investigated the relationship between GJA1 and CD68 expression levels within the tumour microenvironment, with CD68 being a well‐established marker for macrophages." (PMID 39592436, 2024). "The log-ratio of gut-resident microbial genera positively correlated with radiological response to AtzBev and CD8+ T cell infiltration, but was inversely correlated with UPD, HRD and tumour infiltration by CD68+ monocytes." (PMID 39168966, 2024). "Much like tumor-infiltrating lymphocytes (TILs), the numbers of tumor-infiltrated TAMs (F4/80+), and those of M1 (CD68+) and M2 (CD206+) macrophages, were slightly increased by docetaxel treatment but significantly increased by treatment with TH1902." (PMID 38482021, 2024). "High stromal CD68+ and CD163+ TAM infiltration was associated with BC clinicopathological features, increased tumor recurrence and reduced overall survival (OS)." (PMID 39044824, 2024). "All MSI-H CRCs were subjected to digital pathology-based quantification of CD3 + /CD8 + /CD4 + /FoxP3 + /CD68 + /CD204 + /CD177 + tumor-infiltrating immune cells using whole-slide immunohistochemistry." (PMID 39235590, 2024). "Immunohistochemical analysis demonstrated strong positive expression of vimentin (VIM) and CD68 in tumor cells." (PMID 38903727, 2024). "The prognostic value of CD68+CD163+ TAMs was assessed in the tumor nest and stroma of TNBC patients." (PMID 39044824, 2024). "In our tumor mouse model, we observed a significant increase in CD68+ macrophages in response to combination treatment with Gemcitabine and Juzentaihoto." (PMID 39723364, 2024). "Our data highlight the exercise-induced remodelling of peripheral lymphocyte subpopulations and lymphocyte infiltration in prostate tissue, characterized by CD4+, CD8+ and CD68+ cells, which reinforce the anti-tumour role of exercise." (PMID 37171559, 2024). "Treatment notably decreased CD68 + CD163 + macrophages in biopsies from tumor lesions compared to pre-treatment samples in 9 of the 28 patients after 4 weeks." (PMID 38374062, 2024). "In the present study, CD68 was employed as the marker of tumor-infiltrating macrophages, while CD206 was utilized as the marker of M2-type macrophages." (PMID 39742261, 2024). "In OM and PT area, CD68+ macrophages were observed at low frequencies in the tumor capsule as well as along the boundaries of sinusoids and in the stroma of portal spaces." (PMID 38287290, 2024). "To analyze an association of Rep expression with clinic‐epidemiological parameters, we quantified the Rep (and CD68) expression in TMAs including tumor and paired tumor‐adjacent mucosa for each of the 246 patients with automated bright‐field IHC staining." (PMID 36811271, 2024). "mBC bone tissue contains an abundance of stromal cells surrounding the pancytokeratin (PanCK+) mBC tumor cells, including CD68+ cells such as macrophages and CD3+ cells such as T cells." (PMID 38193534, 2024). "On the other hand, the tumor infiltrating immune suppressive cells such as FoxP3+ Tregs and CD68+ macrophages were correlated with inferior outcome." (PMID 38017652, 2024). "We found a moderately positive and statistically significant correlation regarding tumor dimension and CD68 expression at the tumor border." (PMID 39338178, 2024).
tumor (continued). "Our observation revealed higher proportions of CD68+ cells (P < 0.05) and Granzyme B + cells (P < 0.0001) in stroma compared to tumor." (PMID 38799432, 2024). "CD68 infiltration percentage and CD68 touching average were lower in tumours that received NACT (p = 0.02)." (PMID 38674108, 2024). "High levels of infiltrating CD163+ tumor-associated macrophages are associated with a high risk of lymph node metastasis, while high levels of infiltrating CD206+ or CD68+ tumor-associated macrophages are associated with a better prognosis." (PMID 39087027, 2024). "Concurrently, CD68 + TAMs migrate from perivascular locations to vascular-poor regions, generating new tumor vessels and promoting metastasis." (PMID 39068459, 2024). "A decrease in immune infiltration was also observed in NEPC regions of a prostatectomy specimen from a patient with mixed PRAD/NEPC histology, with CD11c+;CD68+ TAMs present within ASCL1+ tumor areas." (PMID 39394434, 2024). "The relationship between IDO1 and marker genes of tumor-associated macrophages (TAMs; CCL5, CD68, and IL10), M1 (IRF5, NOS2, and PTGS2), and M2 (CD163, VSIG4, and MS4A4A) macrophages was analyzed." (PMID 39351094, 2024). "Flow cytometry analysis of fresh tumour samples verified that CCL18 was specifically expressed in CD68+ macrophages in the CRC microenvironment." (PMID 37935468, 2024). "In the phase 2 DAISY trial, the investigators found that CD68-positive tumor cell-proximate macrophages were significantly decreased after T-DXd treatment." (PMID 39164784, 2024). "Ki67 is an important marker reflecting the level of cell proliferation and tumor proliferation, and CD68+ macrophages are used as an indicator of inflammation progression." (PMID 38540144, 2024). "Multiple immunofluorescence analysis shows that tumours in the ‘hot immune’ group have higher numbers of CD68 (mean number: 1142 vs." (PMID 38279874, 2024). "In the xenograft tumor, we also observed an increased infiltration of CD68 macrophages and CD206 immune suppressive macrophages in the miR-27a-3p over-expressing group." (PMID 39742261, 2024). "High stromal CD68+ TAM numbers were linked to higher tumor grade, resulting from tubular architecture modulation by TAMs, whereas high numbers of TAMs in the tumor nest were related to angiogenesis." (PMID 39044824, 2024). "CM from LDHA-inhibited (genetically and pharmacologically) CT2A and GL261 cells impaired the expression of a pro-tumor macrophage marker arginase 1 (Arg1) and the percentage of pro-tumor CD68+CD206+ cells in Raw264.7 macrophages." (PMID 38443336, 2024). "Firstly, we have quantified the proportion of proliferative tumor cells (Sox2+ Ki67+) present in or around the resection cavity borders where we also quantified blood-derived macrophages CD68+ Galectine-3+ and microglia cells TMEM119+Galectine-3−." (PMID 39605004, 2024). "between high CD68 expression in the tumor compartment and poorer PFS and distant metastasis-free survival." (PMID 38357542, 2024). "Differences were also observed in the extravascular matrix pattern, tumour-infiltrating lymphocytes, and tumour-infiltrating CD68+/CD163+ macrophage subsets; although, these differences were not consistent between Regions A and B across the tumours." (PMID 39766052, 2024). "CD68 pan-macrophage marker cannot distinguish between macrophages with anti-tumor effects and those with protumor functions." (PMID 39044824, 2024). "Tumor-associated macrophage markers showed positive correlations, with CCL2 (R = 0.190, P = 1.90E−05*) and CD68 (R = 0.340, P = 6.70E−15*)." (PMID 39030403, 2024). "Immunoistochemically, both benign and malignant tumor cells typically stain positively for S-100, CD68, neuron-specific enolase, CD57, inhibin, calretinin, TFE3, SOX10, and nestin." (PMID 39372871, 2024).
tumor (continued). "Our results demonstrate significant association only with CD68 infiltration percentage per HPF and CD68 touching average, which were significantly lower in tumours of post-neoadjuvant chemotherapy patients." (PMID 38674108, 2024). "We found that CD68 staining was weak to moderate in normal prostate tissue and tumor-adjacent cells but strong in PCa cells." (PMID 38189834, 2024). "In patients with advanced cervical cancer, an increase in the number of CD68+ pSTAT1+ cells in the tumor mass is correlated with longer disease-free survival (DFS) and overall survival (OS)." (PMID 39516356, 2024). "Of note, the tumor-adjacent adipose tissue of obese patients showed a substantially larger increase of CD163+ macrophages (3.7-fold) than for CD68+ (1.7-fold) as compared to normal-weight TNBC patients." (PMID 39456610, 2024). "Meanwhile, FDG uptake in the spleen was positively correlated with the degree of CD8 + T cell lymphocyte, CD20 + B cell lymphocyte, and CD68 + monocyte infiltration in the tumor tissue." (PMID 38627864, 2024). "Elevated expression levels of CD47, CD68, and CD163 are commonly associated with a more immunosuppressive tumor microenvironment, which promotes tumor growth, metastasis, and resistance to treatment." (PMID 39682556, 2024). "Macrophage-related markers, such as CD68, CD204, and CD206, have been used to identify tumor-associated macrophages in the ESCC microenvironment." (PMID 39123188, 2024). "In particular, overweight/obese patients displayed 3.73-fold (p = 0.011) more CD163+ M2-like macrophages in tumor-adjacent adipose tissue as compared to normal-weight patients, whereas the number of CD68+ cells was increased by 1.7-fold (p = 0.038)." (PMID 39456610, 2024). "The qPCR analysis (n = 66) revealed an elevated expression of RUNX1 in tumor tissues (P < 0.0001), and the positive associations between RUNX1 mRNA and CD163 mRNA, Arg1 mRNA, CD68 mRNA, CD206 mRNA, IL-10 mRNA were observed (all P < 0.05)." (PMID 38419056, 2024). "Investigation into sporadic VS growth has shown a positive correlation between immune cell factors such as CD45 and CD68 expression and tumor size and growth rate, as well as elevated CD163 expression in rapidly growing tumors." (PMID 38817895, 2024). "There, TAMs accounted for approximately 18% of total cells in tumor tissue and more than 80% of infiltrating TAMs presented a pro-tumoral M2-like phenotype (CD68+CD163+ cells)." (PMID 39273576, 2024). "The digitized analysis corroborated our initial visual assessment, revealing a notable increase in CD68+ macrophages following combination treatment, particularly at the tumor border." (PMID 39723364, 2024). "The statistical analysis indicated that the expression of the general macrophage marker CD68 was higher in tumor tissues compared to adjacent tissues." (PMID 39531417, 2024). "PD-L1 expression correlated with the presence of CD8+T cells irrespective of their location, showing a stronger correlation in the tumor center, with CD68+ macrophages only in the tumor center and with CD163+ macrophages only at the tumor margin." (PMID 39338178, 2024). "Subsequent research has unveiled the heterogeneity of CD68 + TAMs, constituting distinct subgroups capable of adapting to various stimuli in the tumor microenvironment, thereby polarizing into different phenotypes." (PMID 38273373, 2024). "Among these studies, 13 studies used CD68 as a biomarker for TAM identification in tumor tissue, while five and three studies used CD163 and CD204, respectively." (PMID 38501293, 2024). "High expressing CD68+ TAMs were appreciated at a median density of 19.5 cells per mm2, with a higher abundance in the stroma than the tumor (medians of 35.48 cells per mm2 vs. 6.12 cells per mm2, respectively P < 0.0001)." (PMID 38822345, 2024).